RPS8P6 (ribosomal protein S8 pseudogene 6)
Synonyms: RPS8_1_339
Gene: Processed pseudogene on chromosome 3 (308,714 to 309,322, reverse strand). Ensembl gene ENSG00000231660.
Diseases named in the same sentence as RPS8P6 in open-access papers:
RPS8P6 is named in the same sentence as 1 disease in open-access papers, as found by Europe PMC text mining. Sharing a sentence is not in itself a finding about the gene and the disease. The quoted sentences say what the papers report.
glioblastoma (1 paper, 2023). The most malignant astrocytic tumor (WHO grade IV). "From this analysis, we found ten DEGs specific to IDH1-wt glioblastoma, namely, S100A11, AC091932.2, PIGH, AC020910.5, RPS8P6, AC105339.6, AL589986.1, AL049874.3, CEBPD, and Z99496.1." (PMID 37568598, 2023).